CD4 (CD4 molecule)
Diseases named in the same sentence as CD4 in open-access papers (continued):
Sharing a sentence is not in itself a finding about the gene and the disease.
COVID-19 (continued). "In addition, some studies illustrate that patients infected with COVID-19 exhibited elevated plasma levels of IL-23 and IL-17, along with increased levels of IL-17A-producing CD4+ and CD8+ T lymphocytes." (PMID 38020100, 2023). "However, while CD8+ T cells showed greater reactivity in individuals recovered from mild cases of the disease, the response of CD4+ T cells was predominant in individuals who had severe COVID-19, indicating possible protective role for CD8+ T cells." (PMID 38022506, 2023). "These distinctions have clinical relevance: for example, extensive CD4+ T-cell lymphopenia (<200 cells/mm3) may occur with IHG-II during acute COVID-19 vs. with IHG-IV during advanced HIV disease." (PMID 37311745, 2023). "Notably, the aggregate data demonstrates that HIV-uninfected individuals with COVID-19 displayed elevated levels of HCoV-NL63 specific CD4+ T cells compared to PLWH and healthy controls." (PMID 38343437, 2023). "Further analysis reveals that decreased antibody and CMI responses are associated with reduced circulating follicular helper T cell (TFH) counts and aberrant CD4/CD8 ratios, respectively, indicating that dysregulation of CD4+ T cells by SIV infection impairs the COVID-19 vaccine-induced immunity." (PMID 36239345, 2023). "In severe COVID-19, CD4 + CTLs are substantially enlarged in the lung parenchyma." (PMID 36679947, 2023). "Moreover, we observe 42 conserved CDR3 sequences when comparing the union set of disease-associated CDR3 sequences for ISB-S CD4 samples, the union set of disease-associated CDR3 sequences for ISB-S CD8 samples, and COVID-19 CDR3 sequences for the AB samples." (PMID 36670287, 2023). "COVID-19/PLWH with a CD4 count ≤200 cells/μL could be distinguished from those with higher CD4 counts by lower levels of VEGF and higher levels of IL-6." (PMID 37646024, 2023). "Furthermore, our analysis showed strong associations between multiple immune cell types, including memory B cells, CD8+ T cells, CD4+ memory resting T cells, and neutrophils, in both COVID-19 and sepsis." (PMID 37822934, 2023). "Interestingly, we found metal ion homeostasis pathway associated with metallothionein (MT2A, MT1E, and MT1X) genes enriched within CD8+ TCM, CD8+ TEM, and activated CD4+ T cells in the COVID-19 positive individuals." (PMID 37886355, 2023). "Interestingly, there was a substantial increase in CD4+CD39+ T-cells in COVID-19 patients compared to controls (30 ± 3.4 vs. 6.8 ± 0.66; p < 0.0001)." (PMID 38139439, 2023). "In the peripheral blood of COVID-19 patients, the number of CD4+ T cells is significantly reduced." (PMID 36769328, 2023). "Clonality analyses revealed that COVID-19 patient samples from the ISB-S CD4, ISB-S CD8, and WHH datasets had fewer total unique clonotypes compared to healthy donor controls in these respective datasets, demonstrating the consistency of this observation in multiple sources of TCR data." (PMID 36670287, 2023). "Moreover, single-cell analysis in severe COVID-19 patients revealed that CD4+ T cells are hyperactivated, but Foxp3 expression is repressed." (PMID 37809093, 2023). "In severe COVID-19, CD4+ CTLs may be just as likely to induce viral clearance as CD8+ T cells and may also contribute to lung inflammation." (PMID 36679947, 2023). "However, the percentages of naïve and effector CD4+ memory T cells were comparable among unvaccinated total and vaccinated Omicron COVID-19 patient groups and uninfected controls." (PMID 37881339, 2023). "Surprisingly, there was a comparable breadth of individual NSP12 peptide-specific CD4+ T-cell responses between COVID-19 patients (mean: 12.82 responses; range: 0–25) and seronegative controls including pre-pandemic samples (mean: 12.71 responses; range: 0–21)." (PMID 37215095, 2023). "Low CD4+T counts with superimposed lymphopenia may have an adverse effect on PLWH due to COVID-19 and worsen the disease outcomes." (PMID 37243203, 2023).
COVID-19 (continued). "Since HIV replication gradually destroys the naive and memory CD4+ T-lymphocytes, incapacitating the immune system, low CD4 counts due to COVID-19/HIV co-infections could result in reduced immune response contributing to less COVID-19 complications." (PMID 36776887, 2023). "SARS-CoV-2 induces reactive cytotoxic CD4+ T cells (CD4-CTLs) in COVID-19 patients." (PMID 37388738, 2023). "Age correlates with COVID-19 disease severity, which may be due to low proportions of naive CD4+ and CD8+ T cells." (PMID 36679947, 2023). "While the frequency of CD4+ and CD8+ T cells from COVID-19 patients was similar to that observed in HD, study of the CD4+ T cell compartment showed increased frequencies of Tconv in MD and SD patients concomitantly with a reduction of Treg populations, which was more pronounced in SD patients." (PMID 37809093, 2023). "Among those with a CD4 > 350 cells/mm3, 138(20.6%) had reported infection with COVID-19." (PMID 38005865, 2023). "Interestingly, when we analyzed CD4+ T helper lymphocytes, we found markedly increased expression of both, Tbet and RORγT in stage IV in comparison to stage I of COVID-19." (PMID 37057213, 2023). "Furthermore, decreased CD4 expression in lymphocyte subsets has also been observed in COVID-19 patients." (PMID 36768914, 2023). "Also, interferon-gamma )IFNγ( producing CD4+ T cells from severe COVID-19 patients are lower than moderate cases." (PMID 37264452, 2023). "Our results sustained the definition of a specific cut-off for senescence immune phenotype (SIP) (≥ 5% of CD4 and ≥ 39.5% of CD8 T-cells), which was correlated to a lower serological response induced by COVID-19 vaccination for CD4 and CD8 SIPhigh (p=0.039 and p=0.049 respectively)." (PMID 37334387, 2023). "A large number of studies have shown that CD4+, CD8+ T cell and NK cell were significantly reduced in COVID-19 patients, and were associated with COVID-19 severity and prognosis, and both CD8+ and CD4+ T cell served as diagnostic markers of COVID-19 and predictors of disease severity." (PMID 37249974, 2023). "In general, the trend of waning protection against severe COVID-19 corresponds to the decline in the titre of neutralizing antibody against Omicron and spike-specific CD4+ and CD8+ T cells in the serum of healthy volunteers three months after the second dose of vaccine." (PMID 37132361, 2023). "In another study, 69 patients who recovered from COVID-19 showed lower proportions of CD4 T and CD8 T cells, but higher proportions of (CD19+) B cells and (CD56+) NK cells at 12- and 16-weeks post-infection, compared with healthy controls matched by sex and age." (PMID 37483545, 2023). "Consequently, individuals recovering from COVID-19 were those able to exhibit a SARS-CoV-2-specific CD4 and CD8 T cell response, along with subsequent increases in antibody titers and memory B cells against infection." (PMID 37897014, 2023). "Additionally, severe COVID-19 patients had greater frequencies of central memory cells within the CD62L+ CD4+ T cells compared to recovered patients (p=0.03)." (PMID 36817450, 2023). "Together, these data imply that primary mRNA COVID-19 vaccination may drive T-cell responsiveness towards the CD4+ subset, whereas a priming SARS-CoV-2 infection may drive an increase in T-cell responsiveness more profoundly in the CD8+ subset." (PMID 38193077, 2023). "Considering that immunity and inflammatory responses are closely associated with the clinical manifestations of COVID-19 and outcomes, the levels of peripheral CD3+, CD4+, and CD8+ T cells as well as the levels of TNF-α, IL-6, and IL-10 were also determined in this study." (PMID 38249419, 2023). "The lower number of NK cells in the immunocompetent cohort may result from their participation in antiviral immunity, whereas reduced CD4 + /CD8 + T cell ratios among immunocompromised children may be a protective factor against a severe COVID-19." (PMID 36149567, 2023).
COVID-19 (continued). "Also, other studies have described increasing IFNγ-producing Th1 and a higher level of CD4+ T cell activation in COVID-19 patients, leading to worse clinical outcomes." (PMID 36493512, 2023). "While mRNA vaccines can induce strong T-cell responses, evidence suggests that the frequency of spike-specific CD4+ T cells following COVID-19 vaccination may be lower in older adults." (PMID 38035132, 2023). "T-cells in mild COVID-19 are increased and cross-talking well, while in critical COVID-19, the peripheral CD4 and CD8 T cells are less abundant and dysregulated, their status was hyperactivated, manifested by increase of Th17 and Th1 cells, thereby exacerbating inflammation and tissue damage." (PMID 37653459, 2023). "Notably, during SARS-CoV-2 infection, patients with COVID-19 experienced increased secretion or production of IL-6 and IL-8 and an overall decrease in CD4+ and CD8+, as well as T cells." (PMID 38322760, 2023). "Levels of PD-1 and CTLA-4 expressed on both CD4+T and CD8+T were observed to be upregulated in COVID-19 patients, which may reflect an association with the severity of COVID-19." (PMID 37391394, 2023). "In addition, the involvement of the PD-1/PD-L1 axis has been suggested in the pathogenesis of long COVID-19, in which a depletion of CD4+ and CD8+ T-cells was found." (PMID 37959277, 2023). "No significant changes in CD4+ T cell activation, defined by HLA-DR and CD38 expression, were detected; however, both pregnant and nonpregnant women had significant increases in polyfunctional CD4+ T cells expressing granzymes and perforin during acute COVID-19." (PMID 37036008, 2023). "However, the frequency of CD8+ and CD4+ T cells with effector or memory phenotype in COVID-19 is much higher than the frequency of SARS-CoV-2 specific T cells." (PMID 37946732, 2023). "Comparison of immunological markers in PLWH with COVID-19 with low and higher CD4 counts." (PMID 37646024, 2023). "Additional measures against COVID-19 are needed for PLWH who have low CD4 cell count." (PMID 36670363, 2023). "The decrease in proliferative CD4 and their precursor CD4_Naïve T cells may partially suggest a dysregulated adaptive immune response in COVID-19, especially for those patients displaying encephalopathy." (PMID 37848421, 2023). "Furthermore, in COVID-19 recovered patients, CD4+ T cells producing high levels of IFN-γ and IL-2 displayed polyfunctional phenotypes that stimulated long-lasting memory T and B cell populations." (PMID 37334376, 2023). "Interestingly, an imbalance of the lymphocyte subpopulations, characterized by reduced counts of CD4+ and CD8+ T cells and an increase of natural-killer lymphocytes has been implicated as an early marker of mortality in inpatients with COVID-19." (PMID 37859501, 2023). "In the CD4+ T cell compartment 18/21 (86%), 13/19 (68%), and 7/8 (88%) of persons had detectable memory (> 0.01%) after initial vaccination, booster vaccination, or COVID-19 respectively." (PMID 37291575, 2023). "Thus, the median frequency of CD4+ T lymphocytes reaches 0.062% at day 56 but remains lower than the corresponding frequency found in convalescent COVID-19 patients (0.13% in this study)." (PMID 37388738, 2023). "Notably, most lymphocyte populations (including CD8+ T, CD4+ T, NK, γδT cells) were significantly reduced in COVID-19 with acute necrotizing encephalopathy group, suggesting lymphopenia may be a prominent characteristic COVID-19 associated acute necrotizing encephalopathy." (PMID 37848421, 2023). "In addition, single-cell RNA-sequencing investigations have been carried out on circulating T cells in patients with COVID-19, and one study revealed an increase in antigen-specific CD4+ T cells." (PMID 36679947, 2023). "Taken together, COVID-19 is associated with an enhanced expression of the MIF receptor CD74 on total CD4+ and CD8+ T cells independent of the disease severity." (PMID 37946732, 2023). "In patients with severe COVID-19, CD4 and CD8 levels were decreased." (PMID 37896957, 2023).
COVID-19 (continued). "CD4+CD25+ cells are also more elevated in the acute phase of COVID-19 in those who later develop persistent symptoms and could be used as a predictor of PASC." (PMID 38327763, 2023). "Interestingly, the SARS-CoV-2-specific CD4+ T-cell response appears to have the dominant protective role for lessening COVID-19 severity and controlling and clearing infections." (PMID 37513709, 2023). "However, the mobilization of CD8 T lymphocytes seems to represent a very early stage of the immune response to COVID-19 vaccination (within 1 or 2 weeks), followed by a robust CD4 T and B cells increase." (PMID 37316832, 2023). "Furthermore, it has been described a hierarchy of SARS-CoV-2-specific CD4+ T-cell targets, with the majority of the CD4+ T-cell response in COVID-19 cases directed against highly expressed SARS-CoV-2 spike, and less against M and N proteins." (PMID 36992336, 2023). "Activated CX3CR1+ CD8+ T cells and activated HLA-DR+ CD38+ or Ki67+ CD8+ and CD4+ T cells are found to be more abundant in MIS-C than in patients with severe pediatric COVID-19, but HLA-DR+CD38+ CD8+ T cells frequencies decreased in the first two weeks of admission in MIS-C." (PMID 36982783, 2023). "CD4+ T-cell responses against CCCs are both increased and decreased in COVID-19 patients." (PMID 37215095, 2023). "Conversely, CD73 expressing CD4+ T cells were significantly lower in all three groups of COVID-19 patients compared to HCs, with patients infected with the Wuhan strain exhibiting a more pronounced depletion of CD73+CD4+ T cells when compared with HCs and the other two COVID-19 cohorts." (PMID 37676005, 2023). "Thus, preexisting CD4+ T lymphocytes specific to the immunodominant S816-830 spike epitope are identifiable in 20% of the COVID-19-naïve subjects." (PMID 37388738, 2023). "Expansion of activated CD4+ T and NK T was detected in the COVID-19-positive individuals." (PMID 37886355, 2023). "Male sex is associated with an increased risk of death and OTI in COVID-19 and other coronavirus syndromes, due to a different pattern of the immune response, considering that females had higher CD8+ and CD4+ lymphocyte counts, and stronger immunoglobulin response." (PMID 36672715, 2023). "The analysis of T-cell memory populations comparing samples 5 and 6 after boosting suggests a more dynamic behavior in COVID-19-recovered individuals, with reduced central memory CD4+ T and naïve CD8+ cells and a concomitant increase in effector memory CD8+ T cells." (PMID 37153580, 2023). "During COVID-19 early convalescence about 10% of the virus-reactive CD4+ T cells may also express CXCR5." (PMID 37388738, 2023). "On day 0, lymphopenia and leucopenia were detected in most patients with COVID-19, as well as an increase in the percentage of banded neutrophils, B cells, and CD4+ Treg cells, and a decrease in the content of PD-1low T cells, classical, plasmacytoid, and regulatory dendritic cells." (PMID 37034572, 2023). "In addition to diffuse alveolar injury with severe inflammatory exudation, COVID-19 patients have immunosuppression due to decrease in CD4+ and CD8+ T cells." (PMID 37020477, 2023). "Despite CD4+Tc lymphopenia having been reported in severe COVID-19 patients in a number of studies, it is highly controversial whether this phenomenon occurs in CD8+Tc." (PMID 37029220, 2023). "Together, this depicts that CD4+ T cell function is maintained during COVID-19 which may benefit the infected patient toward recovery, while impaired CD8+ T cell population could have a plausible contribution toward disease progression and severity." (PMID 37886355, 2023). "In line with that, our results show broad expression of CCR7 within the T cell population in the lungs of prolonged COVID-19, the time when absolute numbers of both CD4+ and CD8+ T cells are found significantly increased compared to all other disease groups analyzed." (PMID 36774347, 2023).
COVID-19 (continued). "Patients treated with ABA displayed, after two doses of COVID-19 mRNA vaccine, an impaired CD4 and CD4/CD8 T cell response with a reduced release of IFN-γ, as well as IFN-γ-inducible chemokines, such as CXCL9 and CXCL10, in response to peptides of the spike protein." (PMID 37316832, 2023). "Nonetheless, we still detected vaccine-induced S-specific CD4+ T cells in our patients, which indicates that mRNA vaccination may even contribute to protection against COVID-19 in these potentially vulnerable patients." (PMID 37019909, 2023). "Patients with severe COVID-19 have marked reductions in the number of CD4 T cells, CD8 T cells, B cells, and natural killer cells, often accompanied by exhausted T cells that exhibit diminished proliferative capacity and over-production of pro-inflammatory cytokines." (PMID 37623583, 2023). "Patients who died from COVID-19 showed a significant increase in CD4, CD68, and CD138." (PMID 37109672, 2023). "However, researchers from China present differing results, according to which the more severe the course of COVID-19 and greater lung involvement, the higher the CD4 + /CD8 + T cell ratio." (PMID 36149567, 2023). "Increased activation of Th17 together with a decreased activity of CD4+ regulatory T lymphocytes (Treg) has been observed in severe COVID-19 patients, while the imbalanced ratio Th17/Treg is strongly associated with hyperinflammation, lung damage and disease pathogenesis." (PMID 36829456, 2023). "The Gil-Mansos group recently conducted a comprehensive FACS analysis comparing a control vs COVID-19 disease group (n = 51) within recovered COVID-19 individuals to demonstrate a significant cell cluster at 10 months after recovery of CD4+ CD45RA− CCR4− CCR10− CD27+ CCR6−CXCR3+ CD127+ cells." (PMID 36851285, 2023). "To conclude, COVID-19 mRNA vaccination could induce only CD4 T cells specific for SARS-CoV-2 spike protein in all treated patients as well as in HC." (PMID 37316832, 2023). "CD4+PD-1CD57+ exhausted T cells are found in COVID-19 patients." (PMID 37228604, 2023). "A decreased expression of IFN-γ on CD4+ T cells has also been shown in severe COVID-19 cases." (PMID 36793739, 2023). "Long-term alterations are found not only in primary B and T cell functions in COVID-19 patients up to 6 months following hospital discharge but also in the vast majority of CD4+ T cell and CD8+ T cell subsets that are critical for the control of intracellular and extracellular pathogen infections." (PMID 35632823, 2022). "The induction of FasL in CD4 T cells upon BNT162b2 boosting might be involved in protective immunity against COVID-19." (PMID 35610643, 2022). "However, in a study concerning the Indians, immune memory was detected among mild COVID-19 patients (28 participants) up to 5 months after recovery in both CD4+ T and B cells, with a minimal contribution from CD8+ T cells." (PMID 35603211, 2022). "When recovered from mild COVID-19, patients seem to exhibit decreased levels of Tregs compared to themselves during hospitalization, and severe convalescents resulted in perturbances in CD4+ Tregs." (PMID 36505489, 2022). "In contrast, SARS-CoV-2 specific CD4+ and CD8+ T cell responses are associated with reduced disease severity and the appearance of SARS-CoV-2-specific T cell responses is delayed and reduced in severe COVID-19 cases." (PMID 35992306, 2022). "This relationship was preserved for effector memory CD4+ T cells in convalescent COVID-19." (PMID 35044955, 2022). "Some CD4+ T cell subsets are reported to be involved in COVID-19 pathogenesis." (PMID 36119105, 2022). "However, recent clinical studies showed that CD3+CD4+CD25hiCD127loFoxP3+ Tregs in PBMCs markedly reduced in severe COVID-19 patients." (PMID 36505489, 2022).